CD44 (CD44 molecule (IN blood group))
Diseases named in the same sentence as CD44 in open-access papers (continued):
Sharing a sentence is not in itself a finding about the gene and the disease.
bladder cancer (continued). "We investigated into RHAMM, CD44 mRNA as a prognostic marker in bladder cancer." (PMID 27595989, 2016). "Moreover, FACS results showed that the CD44+ bladder cancer stem cells in T24 cells decreased either transfected with miR-34a or treated with cisplatin." (PMID 24423412, 2014). "Accordingly, identification of CD44 as a miR-34a target gene may explain, at least in part, why overexpression of miR-34a suppressed the migration, invasion, and angiogenesis of bladder cancer cells." (PMID 25551284, 2014). "Some previous studies indicate that CD44 promotes the invasion and angiogenesis of tumor cells; we further investigated the effects of miR-34a overexpression and CD44 restoration on cultured bladder cancer cells." (PMID 25551284, 2014). "Subsequently, we proved that restoration of CD44 could rescue the antitumor effects of miR-34a by co-transfection of miR-34a mimics and CD44 in bladder cancer cell lines." (PMID 25551284, 2014). "Because above results indicated the negative regulation of CD44 expression by miR-34a, we hypothesized that knockdown of CD44 should have a similar effect on cultured bladder cancer cells." (PMID 25551284, 2014). "Our studies focus on it that microRNA-34a functions as an anti-metastatic microRNA and suppresses angiogenesis in bladder cancer by directly targeting CD44 could further enrich the theory of biology." (PMID 25551284, 2014). "In addition, the expression levels of CD36 and CD44 in exosomes were identified via immunoblotting and flow cytometry, and results of this previous study revealed substantial differences in the expression of CD36 and CD44 between healthy individuals and patients with bladder cancer." (PMID 40612948, 2025). "Moreover, a recent research has found a self‐crosslinkable chitosan–HA dialdehyde nanoparticles could target the delivery of siRNA to T24 bladder cancer cells, which could affect bladder cancer through the interaction of CD44 and HA." (PMID 38783892, 2024). "In addition to detecting the presence of CD44 on the cell surface and quantifying the levels of the protein, additional studies are looking at transcriptomics to identify and eventually quantify the presence and levels of CD44 isoforms being expressed in bladder cancer cells." (PMID 38539529, 2024). "These contrasting conclusions can be explained by the presence of several polymorphisms in CD44, which may or may not have a protective effect on the development of bladder cancer." (PMID 35805028, 2022). "However, the lack of CD24 expression in all metastases and little expression of CD44 in bladder cancer tissues may reflect the wide variety of phenotypes found in malignant cells contributing to the cancer etiology." (PMID 35563359, 2022). "However, considering CD44, a basal-type marker but also a putative mediator of the HA-dependent function of ITIH5, we found a significant impact of ITIH5 on risk for recurrence only in bladder cancers with strong CD44 expression." (PMID 33924987, 2021). "However, the role of cancer stem cell marker CD44 in bladder cancer still remains controversial." (PMID 32434417, 2020). "The highly specific binding of KMP1 to CD44 may be due to O‐linked glycosylation of CD44 mediated by ppGalNAc T1, suggesting that KMP1 will probably be a potential specific therapeutic activity and diagnostic biomarker or targeted agent for bladder cancer." (PMID 29577645, 2018). "Therefore, integrative and standardized studies are necessary to elucidate the role of CD44 and CD44v6 in bladder cancer, as they hold an important biological and clinical value and may serve as therapeutic targets." (PMID 29207682, 2017). "They further showed CD44 expressing subpopulation of cells in serial xenograft experiments with fresh patient samples and the tumorigenicity of CD44+ bladder cancer cells was found to be 10-200 times higher than CD44- bladder cancer cells when transplanted in immunodeficient mice." (PMID 29029546, 2017).
bladder cancer (continued). "Thus CD133+CD44+ cells may be the concentrated CSC subpopulation in bladder cancer cell populations." (PMID 27564296, 2016). "Interestingly loss of CD44 did not induce DR5 or apoptotic signaling in T24T bladder cancer cells with or without AGL expression." (PMID 27595989, 2016). "Thus CD133+CD44+ cells may be the enriched CSC subpopulation in MB49 bladder cancer cell populations." (PMID 26566931, 2015). "To confirm the synergistic effect of CD44 and miR-34a in tumorigenesis, we pulled down the expression of CD44 by specific siRNA resulting in decreased capability of cell angiogenesis, invasion and migration, which is in parallel with miR-34a overexpression in all the bladder cancer cell lines." (PMID 25551284, 2014). "BCSCs, characterized by the CD44+ALDH1+ phenotype, were isolated from SW780 and 5637 bladder cancer cell lines using flow-activated cytometric sorting." (PMID 40635786, 2025). "ATG7 overexpression stabilizes CD44 by upregulating USP28 protein, which in turn modulates stem cell-like properties, invasion and human lung metastasis in bladder cancer." (PMID 40707430, 2025). "The conjugate outperformed single-target GEM conjugates (CD71-GEMs or CD44-GEMs) in terms of binding affinity and inhibitory efficacy, making CD71-CD44-GEMs a promising approach for treating bladder cancer by effectively targeting both cancer cells and CSCs." (PMID 38255292, 2024). "Luminal subtype bladder cancer is defined by cellular markers Uroplakin II and CK20, while basal bladder cancer cells are defined most by CK5/6 and CD44." (PMID 38539529, 2024). "This study aimed to classify bladder cancer subtypes using a panel of IHC markers (CK5/6 and CD44 for basal; GATA3 and CK20 for luminal) widely used in surgical pathology." (PMID 39768377, 2024). "The CD44+ALDH1A1+ subpopulation, which is referred to as bladder cancer stem cells (BCSCs), displayed enhanced tumor sphere formation and resistance to cisplatin." (PMID 38191448, 2024). "Following the upregulation of USP28 induced by ATG7, CD44 can be deubiquitinated and stabilized by USP28, which mediates the enhancement of the cancer stem cell-like properties of bladder cancer." (PMID 36879346, 2023). "Blocking and knock-down studies pointed to the influence of integrin α5, CD44, and the Cyclin–CDK axis in regulating bladder cancer growth." (PMID 37835543, 2023). "Bladder cancer patients with a high NANOG and CD44 expression had poorer recurrence-free survival and overall survival rates." (PMID 37627900, 2023). "CD44, CD133, and other markers are expressed in both the basal cell layer and bladder cancer stem cells." (PMID 35342431, 2022). "-The TET1/USP28/CD44/RhoGDIβ pathway was identified as the regulator of the oncogenic activities of ATG7 for stem-like property, invasion, and lung metastasis of human bladder cancer cells." (PMID 35269796, 2022). "Bladder cancer stem cells have been described by expression of stem cell markers, among them CD24, CD44, and CD47, respectively." (PMID 35682984, 2022). "When co-expressed with basal markers CK5/6 and CD44, FAP was a strong prognosticator of disease-specific survival in bladder cancer." (PMID 36313650, 2022). "The expression of bladder cancer stem-cell markers CD24 and CD44 was investigated on organoids as well." (PMID 35628262, 2022). "Noteworthy, EGCG suppresses Sonic signaling to decrease CD44, CD133, Nanog, Oct4 and ALDH1 in bladder cancer therapy." (PMID 34769099, 2021). "Next, we stained n = 52 bladder cancer tissues for ITIH5 and CD44 protein expression by immunohistochemistry." (PMID 33924987, 2021). "In previous studies, ABCG2, CD44, and CD133 were used to identify and isolate the bladder cancer stem cells." (PMID 33363019, 2020).
bladder cancer (continued). "Other studies using PDX models of bladder cancer have demonstrated that CD49f, in conjunction with surface antigens such as CD44, CK20, CD4714, and CD9015, discriminate poorly differentiated (basal) from differentiated bladder cancer cells." (PMID 32439865, 2020). "As compared with the matched primary tumors, most recurrent bladder cancer cells (RB1 and RB3) possessed a higher percentage of CD44- and 67LR-positive populations." (PMID 28423359, 2017). "The CD44 and Hyaluronan Mediated Motility Receptor (RHAMM) regulate the growth of bladder cancer cells." (PMID 29221154, 2017). "These experiments show that loss of HA synthesis by genetic alteration (inhibition of HAS2 expression) or by an inhibitor (4MU) or addition of superfluous HA have little effect on CD44 and RHAMM expression in UMUC3 and T24T bladder cancer cells." (PMID 27595989, 2016). "CD44 and RHAMM both play a role in inhibiting anchorage dependent and independent growth of bladder cancer cells with low AGL expression." (PMID 27595989, 2016). "This demonstrates that HA interaction with both CD44 and RHAMM gives rise to similar proliferative signaling in the AGL low bladder cancer cells." (PMID 27595989, 2016). "The mechanism how CD44 and RHAMM drives growth of bladder cancer cells that have lost AGL will be investigated in future." (PMID 27595989, 2016). "Here we focus on the importance of CD44 and RHAMM in driving the rapid growth of bladder cancer cells with low AGL expression." (PMID 27595989, 2016). "Here we aim to study the role of CD44 and RHAMM, downstream of HA, in rapid growth of bladder cancer cells driven by low AGL expression." (PMID 27595989, 2016). "Tumor-initiating cells (TICs; lineage CD44+, CK5+, CK20−) in human bladder cancer have been isolated and a cell line established." (PMID 25658794, 2015). "Invitro knock-down of RHAMM, CD44 and HAS isoenzymes was achieved by siRNA and lentiviral shRNA in J82 bladder cancer cells." (PMID 24069434, 2013). "In five bladder cancer datasets (TCGA-MIBC, GSE13507, GSE48075, GSE32894, and GSE48276), ERBB2 was highly positively correlated with GATA3 and FOXA1 but negatively correlated with CD44 and KRT5, suggesting that ERBB2 is a luminal marker to some extent." (PMID 39840049, 2024). "However, different biomarkers (Lineage−CD44+CK5+CK20−, BCMab1+CD44+, CD31−CD45−CD44+, MUC1−CD44v6+) have been used to isolate bladder cancer stem cells in different studies." (PMID 38191448, 2024). "Furthermore, MARCH7 overexpression led to a decrease in the expression of stemness markers, such as OCT4, CD44, and CD133, in bladder cancer stem cells." (PMID 38462600, 2024). "CD44 could be a promising tool to address the TME and improve bladder cancer therapy as already demonstrated for pancreatic ductal adenocarcinoma." (PMID 37781195, 2023). "In bladder cancer tissue, epithelial membrane antigen (EMA) negative CD44 variant subtype (CD44v6) positive cells account for about 30% of cancer cells." (PMID 35342431, 2022). "CD44 is related to tumor heterogeneous adhesion and other functions, while ITGB1 has been confirmed to be involved in the occurrence and development of gastric, pancreatic, and bladder cancers, and is closely related to cellular immunity and immunosuppression." (PMID 34931260, 2022). "In addition, paraffin sections from bladder cancer tissue and metastases in lymph nodes were investigated for expression of CD276, CD24, and CD44." (PMID 35563359, 2022). "Furthermore, CPX treatment reduced the expression of bladder cancer stem cell marker proteins SOX9 and CD44." (PMID 34059639, 2021). "Pooled data showed that CD44 expression was significantly lower in bladder cancer than in non-tumor tissue samples." (PMID 32434417, 2020). "In conclusion, the current study showed that CD44 expression in bladder cancer was lower than in non-tumor tissue samples." (PMID 32434417, 2020).
bladder cancer (continued). "CD44 expression in bladder cancer was lower than in non-tumor tissue samples (OR = 0.14, P = 0.005), which was consistent with TCGA data." (PMID 32434417, 2020). "Data from five studies included 197 patients with bladder cancer and 69 non-tumor tissue samples, which showed that CD44 expression was lower in bladder cancer than in non-tumor tissue samples (OR = 0.14, 95% CI = 0.04–0.54, P = 0.005)." (PMID 32434417, 2020). "The clinical effect of CD44 expression in patients with bladder cancer has not been clearly investigated." (PMID 32434417, 2020). "Our previous studies showed that glycopeptide‐preferring polypeptide GalNAc transferase 1 (ppGalNAc T1) mRNA was highly expressed in bladder tumor tissues and bladder cancer stem cells, and GALNT1‐positive staining in bladder cancer tissues was related to CD44 staining." (PMID 29577645, 2018). "Moreover, we have also demonstrated that Oct4-regulated oncolytic adenovirus can kill CD44- and CD133-positive bladder cancer cells." (PMID 27244887, 2017). "These experiments suggest that high CD44 mRNA expression is not a predictor of poor bladder cancer patient outcome even though CD44 is an important contributor in tumor growth and metastasis." (PMID 27595989, 2016). "Western blot analysis and Terminal deoxynucleotidyl transferase (TdT) dUTP Nick-End Labeling (TUNEL) assay was carried out to study cellular apoptosis with HAS2, CD44 and RHAMM loss in bladder cancer cells with and without AGL expression." (PMID 27595989, 2016). "CD44 and CD47 are both supposed to be biomarkers of bladder cancer TICs." (PMID 25658794, 2015). "Histological tests for bladder cancer primary transplant nodules in nude mice showed that CD44 and CD47 were highly expressed in the outer rim of cells in tumor nodules, but most internal cells in the nodules are CD44-low and CD47-low." (PMID 25658794, 2015). "Then western blotting, showed that stable transfection of miR-34a precursor resulted in decreased protein levels of CD44 in bladder cancer cells, when compared with negative control." (PMID 25551284, 2014). "Interestingly, the mean urinary CD44 concentration was higher in subjects without bladder cancer than in those with bladder cancer (117.22 ng/mL vs. 53.09 ng/mL, p < 0.0001)." (PMID 41440277, 2025). "In bladder cancer, a direct role for CD44 in promoting chemoresistance has not been discovered." (PMID 38539529, 2024). "Future anti-CD44 investigations should look at earlier bladder cancer stages and in non-muscle-invasive disease, with the advantage of the latter being the ability to deliver the therapy intravesically, which will likely reduce side effects associated with systemic monoclonal antibody therapy." (PMID 38539529, 2024). "CD44+CK5+CK20− bladder cancer cells were BCSCs; CK20 was not expressed in these cells." (PMID 35342431, 2022). "We hypothesize that pathways regulating CD276—a bladder cancer cell and/or stem cell marker—are distinct and regulated independently from the other cancer stem cell markers investigated—i.e., CD24, CD44, and the ALDH1 paralog A1—and independent from the regulation of cell proliferation." (PMID 35563359, 2022). "Namely, MUC16 scored 10/15 (not highlighted in the Target Score graph) and, more strikingly, CD44 (not highlighted in the Target Score graph), one of the most studied glycoproteins in bladder cancer, frequently suggested as a biomarker of cancer stem cells, scored 5/15." (PMID 34108014, 2021). "Also, both HAS, HYAL1, CD44 and RHAMM were found to be overexpressed in bladder cancer tissues." (PMID 29207682, 2017). "Interestingly when we knocked down HAS2 or treated with 4MU, UMUC3 and T24T bladder cancer cells +/− AGL expression had no change in their CD44 and RHAMM expression." (PMID 27595989, 2016). "However HA interaction with CD44 and RHAMM has identical effect on bladder cancer cell growth." (PMID 27595989, 2016).
bladder cancer (continued). "However the role of HA receptors CD44 and Hyaluronan Mediated Motility Receptor (RHAMM) in regulating the growth of bladder cancer cells driven by loss of AGL has not been studied." (PMID 27595989, 2016). "Interestingly loss of HAS2 does not reduce expression of CD44 and RHAMM in bladder cancer cells irrespective of AGL expression status." (PMID 27595989, 2016). "However, results from other research have proved that it is not an increase but a decrease of CD44 expression that appears as an unfavorable prognostic factor in bladder cancer." (PMID 23445749, 2013). "In addition, we found that ITPR3 accelerated the malignant progression of bladder cancer by promoting proliferation, metastasis, and cancer stemness in vitro and in vivo, and in this process, the role of the NF-κB/CD44 signaling pathway could not be neglected." (PMID 33573671, 2021). "However, the function of CD44 in bladder cancer has not yet been fully clarified." (PMID 25551284, 2014). "We selected cell line models for basal-type bladder cancers with squamous features (SCaBER cell line) and without (HT1376), in addition showing differential CD44 expression levels." (PMID 33924987, 2021). "Treatment with superfluous amounts of LMW HA had little impact on CD44 and RHAMM expression of UMUC3 and T24T bladder cancer cells irrespective of AGL expression status." (PMID 27595989, 2016).